RNU6-220P (RNA, U6 small nuclear 220, pseudogene)
Gene: Small nuclear RNA gene on chromosome 8 (143,350,172 to 143,350,278, forward strand). Ensembl gene ENSG00000212221.
Homologues: Orthologues: chimpanzee U6 (94% identical), macaque U6 (92% identical), dog U6 (77% identical), dog U6 (72% identical). Paralogues in human: RNU6-1331P (82% identical), RNU6-31P (81% identical), RNU6-1274P (80% identical), RNU6-1287P (80% identical), RNU6-242P (80% identical), RNU6-727P (80% identical), RNU6-797P (80% identical), RNU6-842P (80% identical), RNU6-1011P (79% identical), RNU6-11P (79% identical), RNU6-12P (79% identical), RNU6-13P (79% identical), and 1284 more.